SNRNP48 (small nuclear ribonucleoprotein U11/U12 subunit 48)
Description:
Likely involved in U12-type 5' splice site recognition.
Synonyms: C6orf151; FLJ32234; dJ512B11.2; dJ336K20B.1
Tractability: Small molecule: a structure with a bound ligand is known. PROTAC: UniProt records ubiquitination sites on it; ubiquitination databases record sites on it.
Gene: Protein-coding gene on chromosome 6 (7,590,189 to 7,611,967, forward strand). Ensembl gene ENSG00000168566.
Subcellular location: Nucleus
Subcellular location (Human Protein Atlas): Nucleoplasm; Cytosol
Pathways (Reactome):
Metabolism of RNA: mRNA Splicing - Minor Pathway
Gene Ontology:
Molecular function: protein binding
Biological process: mRNA splicing, via spliceosome; RNA splicing; spliceosome conformational change to release U4 (or U4atac) and U1 (or U11)
Cellular component: nucleoplasm; spliceosomal complex; U11/U12 snRNP; U12-type precatalytic spliceosome; U12-type spliceosomal complex; nucleus
Genetic constraint (gnomAD): Loss-of-function variants: 22 observed, 22.92 expected, observed/expected ratio (o/e) 0.96, 90% interval 0.69 to 1.37. The upper end of that interval is the gene's LOEUF score, 1.37, which puts it in group 5 of 6, group 1 being the genes least tolerant of losing a copy. Missense variants: 227 observed, 238.92 expected, observed/expected ratio (o/e) 0.95, 90% interval 0.85 to 1.06. Synonymous variants: 69 observed, 79.45 expected, observed/expected ratio (o/e) 0.87, 90% interval 0.71 to 1.06.
Homologues: Orthologues: chimpanzee SNRNP48 (99% identical), macaque SNRNP48 (99% identical), dog SNRNP48 (91% identical), guinea pig SNRNP48 (91% identical), pig SNRNP48 (87% identical), mouse Snrnp48 (87% identical), rabbit SNRNP48 (87% identical), rat Snrnp48 (84% identical), tropical clawed frog snrnp48 (50% identical), zebrafish snrnp48 (42% identical). Paralogues in human: GTSF1 (9% identical), GTSF1L (9% identical).
Diseases named in the same sentence as SNRNP48 in open-access papers:
SNRNP48 is named in the same sentence as 3 diseases in open-access papers, as found by Europe PMC text mining. Sharing a sentence is not in itself a finding about the gene and the disease. The quoted sentences say what the papers report.
COVID-19 (1 paper, 2022). A disease caused by infection with severe acute respiratory syndrome coronavirus 2. "Of note, we observed numerous DTU genes involved in RNA splicing, with 10 genes (e.g. HNRNPC, SNRPD3, QKI, and LUC7L2) increased major transcript usage and 18 genes (e.g. SNRNP48, NCBP1, CELF2, RALY, and PABPC1) decreased major transcript usage in the COVID-19 patients." (PMID 35421082, 2022).
tumor (2 papers, 2020). "Except for three RBPs (SNRNP48, DDX6, and ZC3HAV1) out of the 63, the high-expression tumor group had worse clinical outcome for RBPs that were upregulated in IR-1." (PMID 33311498, 2020).
SNRNP48 also shares sentences with these, for which no sentence is quoted: cancer (1 paper).